RNU11-5P (RNA, U11 small nuclear 5, pseudogene)
Gene: Small nuclear RNA gene on chromosome 14 (29,476,784 to 29,476,912, forward strand). Ensembl gene ENSG00000212518.
Homologues: Orthologues: chimpanzee RNU11-5P (100% identical), macaque RNU11-5P (94% identical). Paralogues in human: RNU11-3P (69% identical).